LRRC23 (leucine rich repeat containing 23)
Description:
Essential for sperm motility and male fertility. Plays an important role in the proper assembly of the third radial spoke (RS3) head and the bridge structure between RS2 and RS3 in the sperm flagella.
Synonyms: LRPB7; B7; SPGF92
Tractability: No criterion of Open Targets' tractability assessment is met for any kind of drug.
Gene: Protein-coding gene on chromosome 12 (6,873,569 to 6,914,241, forward strand). Ensembl gene ENSG00000010626.
Subcellular location: Cell projection, cilium, flagellum; Cytoplasm, cytoskeleton, flagellum axoneme; Cytoplasm
Subcellular location (Human Protein Atlas): Nucleoli; Nucleoli rim
Gene Ontology:
Molecular function: protein binding
Biological process: flagellated sperm motility; radial spoke assembly
Cellular component: cytoplasm; sperm flagellum; cytosol; motile cilium
Genetic constraint (gnomAD): Loss-of-function variants: 28 observed, 39.33 expected, observed/expected ratio (o/e) 0.71, 90% interval 0.53 to 0.98. The upper end of that interval is the gene's LOEUF score, 0.98, which puts it in group 4 of 6, group 1 being the genes least tolerant of losing a copy. Missense variants: 377 observed, 435.27 expected, observed/expected ratio (o/e) 0.87, 90% interval 0.8 to 0.94. Synonymous variants: 161 observed, 174.81 expected, observed/expected ratio (o/e) 0.92, 90% interval 0.81 to 1.05.
Homologues: Orthologues: chimpanzee LRRC23 (99% identical), macaque LRRC23 (96% identical), dog LRRC23 (85% identical), rabbit LRRC23 (84% identical), guinea pig LRRC23 (81% identical), rat Lrrc23 (79% identical), mouse Lrrc23 (78% identical), tropical clawed frog lrrc23 (57% identical), pig LRRC23 (54% identical), zebrafish lrrc23 (45% identical), Drosophila melanogaster TbCMF46 (13% identical), Drosophila melanogaster Ppr-Y (12% identical). Paralogues in human: CEP97 (20% identical), LRGUK (18% identical), DNAAF1 (16% identical), LRRC9 (16% identical), LRRC46 (15% identical), LRRC49 (15% identical), DRC3 (15% identical), LRRC43 (14% identical), LRRCC1 (13% identical), LRRIQ3 (13% identical), PPP1R42 (13% identical), DNAAF11 (12% identical), and 1 more.
Diseases named in the same sentence as LRRC23 in open-access papers:
LRRC23 is named in the same sentence as 6 diseases in open-access papers, as found by Europe PMC text mining. Sharing a sentence is not in itself a finding about the gene and the disease. The quoted sentences say what the papers report.
asthenozoospermia (1 paper, 2023). "A bi-allelic splicing donor site variant in LRRC23 was identified from asthenozoospermia patients." (PMID 38091523, 2023).
infertile (1 paper, 2023). "Our study provides new insights into the structure and function of RS3 in mammalian spermatozoa and the molecular pathogenicity of LRRC23 underlying reduced sperm motility in infertile human males." (PMID 38091523, 2023). "From infertile male patients with defective sperm motility, we identified a splice site variant of LRRC23." (PMID 38091523, 2023). "Consistent with the ASZ phenotype in our infertile patients with a new splice mutation in LRRC23, genetic ablation of Lrrc23 in mice causes severe sperm motility defects and male infertility." (PMID 38091523, 2023).
male infertility (1 paper, 2025). The inability of the male to effect fertilization of an ovum after a specified period of unprotected intercourse. "Strikingly, in mice and humans, mutations in CFAP61, CFAP91, CFAP251, and LRRC23 cause male infertility but not primary ciliary dyskinesia or hydrocephalus, suggesting more differences in the RS3 structure and/or function between sperm flagellum and cilia in multiciliated cells." (PMID 40886204, 2025). "Damaging mutations in genes encoding RS1 and RS2 components cause PCD, while mutations in genes encoding RS3 proteins, CFAP61, CFAP91, CFAP251, and LRRC23 result in male infertility but not PCD." (PMID 40886204, 2025).
LRRC23 also shares sentences with these, for which no sentence is quoted: ciliopathies (1 paper); renal clear cell carcinoma (1); tumor (1).